SPARC (secreted protein acidic and cysteine rich)
Diseases named in the same sentence as SPARC in open-access papers (continued):
Sharing a sentence is not in itself a finding about the gene and the disease.
aneurysm (5 papers, 2013 to 2025). Bulging or ballooning in an area of an artery secondary to arterial wall weakening. "The results of this study suggest that SPARC has a pathogenic role in the alteration of the extracellular matrix of intracranial arteries during aneurysm formation." (PMID 23516489, 2013). "Although the number of VSMCs in the aneurysm wall was reduced and the alignment was disordered, the expression of SPARC was increased and the expression of HK2 was significantly reduced compared to normal vascular tissue." (PMID 38076208, 2023). "Reactive oxygen species, serine proteases and pro-inflammatory cytokines are adverse factor for aneurysms and have vital correlation with SPARC and matrix metalloproteinase expressions." (PMID 23516489, 2013). "In the aneurysm group, both unruptured aneurysms (patients 1–4) and ruptured aneurysms (patients 5–31) exhibited moderate to extensive staining of medial smooth muscle cells for both SPARC and MMP-2/-9." (PMID 23516489, 2013). "It was found that SPARC was remarkably increased in IA samples from both datasets, and its expression was higher in ruptured aneurysms than in unruptured aneurysms, suggesting that the high expression of SPARC may increase the risk of ruptured IA." (PMID 38076208, 2023). "All of these results imply that SPARC may have a role in the development of aneurysms." (PMID 23516489, 2013). "In our other dataset (GSE54083), we were surprised to find that the expression of CDH11, SPARC, FN1, and FSTL1 in unruptured aneurysms was significantly increased, while WNT11, PCDH9, and GPC3 expression levels were relatively low." (PMID 34997174, 2022). "We observed qualitatively the immunohistochemical staining of SPARC, MMP-2 and MMP-9 for each aneurysm and control artery and assigned each protein a grade ranging from negative staining to extensive staining in intimal and medial smooth muscle cells." (PMID 23516489, 2013). "In this paper, we reported a cohort of patients diagnosed as intracranial aneurysms with obviously increase of SPARC, MMP2 and MMP9 in their pathological aneurysm tissue." (PMID 23516489, 2013). "The SPARC, MMP-2 and MMP-9 protein expression levels in aneurysms were investigated by immunohistochemistry, western blot and correlative analysis of their expression levels with clinicopathologic factors was performed." (PMID 23516489, 2013). "It was found that the expression levels of CDH11, SPARC, FN1, and FSTL1 genes in unruptured aneurysms were higher than those in healthy samples, while the expression levels of WNT11, PCDH9, and GPC3 in unruptured aneurysms were lower than those in healthy samples." (PMID 34997174, 2022).
atherosclerosis (5 papers, 2016 to 2025). A disease characterized by the build-up of fatty material and calcium deposition in the arterial wall resulting in partial or complete occlusion of the arterial lumen. "SPARC induces angiogenesis after cortical injury, and SPARC expression is increased in patients with atherosclerosis and calcified plaques." (PMID 37794518, 2023). "The subsequent secretion of SPARC proteins into circulation may trigger inflammation, vascular endothelial cell apoptosis, and vascular smooth cell proliferation to initiate atherosclerosis." (PMID 30875406, 2019).
colon adenocarcinoma (5 papers, 2010 to 2025). "The genes positively correlating with SPARC in breast and colon adenocarcinoma tumors included TGFB1, a powerful stimulator of migration of peritumoral CAFs." (PMID 36604669, 2023).
COVID-19 (5 papers, 2022 to 2023). A disease caused by infection with severe acute respiratory syndrome coronavirus 2. "The potential anticancer property of SPARC is also worth mentioning in this context, since cancer might increase the risk of COVID-19 adverse outcomes." (PMID 37233608, 2023). "Using open-access databases and clinical retrospective studies, we noticed that serum CRP interacted with circulating megakaryocytes through SPARC and further regulated virus response and systematic inflammation in COVID-19 patients." (PMID 38077346, 2023). "Secreted protein acidic and rich in cysteine (SPARC) is a biomolecule that is associated with various properties and functions that situate it as a candidate which may be used to prevent, treat and manage COVID-19 as well as the post-COVID-19-era health problems." (PMID 37233608, 2023). "Several lines of evidence suggested that MKs were significantly accumulated in progression/severe COVID-19 as a feature of the systemic inflammatory response, with SPARC being the marker gene." (PMID 38077346, 2023). "Our research proposed the possibility of megakaryocytes influencing inflammation response during COVID-19 through the SPARC-mCRP link." (PMID 38077346, 2023). "Progression to fibrosis in severe COVID-19 is associated with overexpression of fibrogenic pathways and increased in CTHRC1- and SPARC-positive pFBs." (PMID 36405615, 2022). "In summary, our study shows that progression to fibrosis in severe COVID-19 was associated with overexpression of fibrogenic pathways and increased in CTHRC1- and SPARC-positive pFB." (PMID 36405615, 2022). "We observed a statistically significant increase of SPARC expression in COVID-19 samples compared with control samples." (PMID 36405615, 2022). "Since pCRP dissociates into mCRP to promote inflammation, we proposed that the SPARC-mCRP linking may further aggravate inflammation status in COVID-19 patients." (PMID 38077346, 2023). "The observed correlation between CRP and megakaryocytes, along with the potential interaction with SPARC, suggests that megakaryocytes could play a role in the immune response to COVID-19." (PMID 38077346, 2023). "The interaction between CRP and SPARC may affect the immune response and viral clearance in COVID-19." (PMID 38077346, 2023). "The interaction between CRP and SPARC expressed by megakaryocytes may modulate the immune response and contribute to regulating viral clearance and inflammation in COVID-19 patients." (PMID 38077346, 2023). "DNMT3B, LAMC1, MET, NASP, PTEN, and SPARC are upregulated in COVID-19." (PMID 36204652, 2022). "Although the expression of SPARC was consistently increased in some sc-RNA-Seq datasets of COVID-19 patients, no previous studies have analyzed its expression during the different phases of DAD nor its tissue distribution." (PMID 36405615, 2022). "However, the roles of LAMC1, MET, NASP, and SPARC in COVID-19 have not yet been elucidated." (PMID 36204652, 2022). "Whereas these previous observations clearly demonstrated that SPARC is involved in the development of IPF, its possible role in other pulmonary lesions, including COVID-19 DAD, was not previously evaluated in deep." (PMID 36405615, 2022).
diffuse large B-cell lymphoma (5 papers, 2013 to 2024). "However, high SPARC expression is associated with a good prognosis in diffuse large B-cell lymphoma." (PMID 39040110, 2024). "The combined immunohistochemical assessment of Fibronectin and SPARC, two components of the extracellular matrix, represents an important tool for the prediction of survival in diffuse large B-cell lymphomas." (PMID 24499539, 2013). "Finally, certain lymphoproliferative diseases are also associated with expression of COL6A1, COL18A1, MMP3 and TIMP1, and a subset of patients with diffuse large B cell lymphoma and adverse prognosis show decreased expression of POSTN, SPARC, COL1A1, COL3A1,CSTK, MMP9 and LAMB3." (PMID 33379263, 2020).
gastric adenocarcinoma (5 papers, 2017 to 2022). "Their obtained result demonstrated that the FN1 expression and SPARC in gastric adenocarcinoma tissues were found to be closely correlated to their poor prognosis." (PMID 35965624, 2022). "The endogenous expression of SPARC in fibroblasts was suppressed by mucus-producing gastric adenocarcinoma cells(MKN-45)." (PMID 29156791, 2017). "Production of SPARC in fibroblasts was reduced by the mucus-producing gastric adenocarcinoma cells." (PMID 29156791, 2017). "The endogenous expression of SPARC in fibroblasts was suppressed while co-cultured with MKN-45 cells, which were derived from human mucus-producing gastric adenocarcinoma." (PMID 29156791, 2017). "The expression of SPARC in 365 primary advanced gastric adenocarcinomas and 39 non-cancerous tissues was evaluated by immunohistochemical staining." (PMID 29156791, 2017).
Hypertension (5 papers, 2013 to 2025). The presence of chronic increased pressure in the systemic arterial system. "Amongst our novel findings is SPARC rs4958487, associated with increased glucose levels and hypertension." (PMID 31891604, 2019). "Among those variants without evidence of previous GWAS relationships, one example of a novel and potentially pleiotropic variant is the intronic SPARC rs4958487-A associated with increased glucose levels and hypertension." (PMID 31891604, 2019). "The present study also showed that SPARC is significantly correlated with risk factors such as hypertension, and this result agrees with our model, which is in accord with previous results." (PMID 23516489, 2013). "Our study provides strong evidence that TNFSF12, SLC22A4, and SPARC may be potential risk factors for hemorrhagic stroke and that their induction of hypertension may be involved in potential pathogenesis." (PMID 38977622, 2025). "Based on our results, we concluded that SPARC correlates with blood pressure and augments vascular inflammation in the setting of hypertension." (PMID 40362650, 2025). "The same report demonstrated that in vivo injection of SPARC increased systolic blood pressure in mice, suggesting that SPARC induces hypertension." (PMID 40362650, 2025). "This is the first description of the novel aspects of SPARC as an early effector of vascular inflammation in the setting of hypertension." (PMID 40362650, 2025). "We investigated the pathophysiological regulation and role of SPARC in vascular inflammation in a rat model of hypertension created using deoxycorticosterone acetate (DOCA, 40 mg/kg/week, s.c.)and salt (1% in drinking water)." (PMID 40362650, 2025). "TNFSF12 promoted IA and SAH, SLC22A4 increased the risk of IA rupture leading to SAH, and SPARC was a risk factor for ICH, for which hypertension may be a potential mediator." (PMID 38977622, 2025). "Analysis of the correlation between SPARC expression and blood pressure and vascular inflammation suggested that the increment in SPARC might induce hypertension and vascular injury." (PMID 40362650, 2025). "Therefore, the observed overexpression of SPARC in this study might have mediated the pathogenesis of hypertension and vascular injury, at least in part, in the early stages of the diseases." (PMID 40362650, 2025). "Clinical studies showing the correlation between plasma SPARC levels and blood pressure and inflammatory markers in plasma indicate that elevation of SPARC and ADAMTS1 might be a possible predictive diagnostic marker for vascular injury in the setting of hypertension." (PMID 40362650, 2025). "The present study might provide future options for selecting SPARC inhibitors in patients with hypertension and hypertensive organ damage who are not eligible to receive renin–angiotensin system inhibitors because of side effects or contraindications." (PMID 40362650, 2025).
intracranial aneurysms (5 papers, 2013 to 2025). "The inhibition of TNFSF12, SLC22A4, and SPARC can reduce the risk of intracranial aneurysm, subarachnoid hemorrhage, and intracerebral hemorrhage." (PMID 38977622, 2025). "It has been reported that secreted protein acidic and cysteine-rich (SPARC) is highly expressed in intracranial aneurysms and is associated with the expression of EMT-related molecules (namely MMP2 and MMP9)." (PMID 34997174, 2022). "The present study showed that SPARC was expressed in 96% (25 of 26) of intracranial aneurysms, a result that is in accord with previous results, and these results confirm the presence of SPARC protein in intracranial aneurysms." (PMID 23516489, 2013). "The results showed that normal Circle of Willis arteries exhibited either minimal or negative staining for SPARC, MMP-2 and MMP-9; however, human intracranial aneurysms stained extensively for both SPARC and MMP-2/-9." (PMID 23516489, 2013). "The results indicate that SPARC is widely expressed in human intracranial aneurysms, and its expression correlates with MMP-2 and MMP-9 expression, age and risk factors but not with the Hunt-Hess grade." (PMID 23516489, 2013). "However, the total number of intracranial aneurysm specimens studied was small (n = 31), and more investigations should be performed to determine the role of SPARC in human intracranial aneurysms." (PMID 23516489, 2013). "Further, the role of MMP-9 could be attributed to the anti-angiogenic effect of SPARC.The role of SPARC in tumors led us to wonder whether it is also involved in the occurrence of intracranial aneurysms." (PMID 23516489, 2013). "The goal of this study was to establish the role of SPARC in human intracranial aneurysms." (PMID 23516489, 2013). "Thirty-one intracranial aneurysms were immunohistochemically stained for SPARC, MMP-2 and MMP-9." (PMID 23516489, 2013). "Combined with previous research, the present study shows that SPARC regulates MMP-2 and MMP-9 expression in human intracranial aneurysms; however, whether SPARC is an upstream or downstream regulatory factor remains to be determined." (PMID 23516489, 2013). "The study showed that SPARC is widely expressed in intracranial aneurysms, and the expression of SPARC is significantly correlated with the expression of MMP-2 and MMP-9, which are by far the proteases that are the most closely related to the pathogenesis of intracranial aneurysms." (PMID 23516489, 2013). "Targeting SPARC may be a novel strategy to delay the development of intracranial aneurysms." (PMID 38076208, 2023). "However, little is known about the expression of SPARC in intracranial aneurysms." (PMID 23516489, 2013). "Our results imply that SPARC may have a role in the progression of intracranial aneurysms, and this finding has great significance in explaining the pathogenesis and clinical treatment of intracranial aneurysms." (PMID 23516489, 2013). "The western blot results showed that the expression levels of SPARC, MMP-2 and MMP-9 were significantly up-regulated in intracranial aneurysms relative to the expression levels in the normal Circle of Willis arteries." (PMID 23516489, 2013). "We found that the expression levels of SPARC, MMP-2 and MMP-9 were significantly up-regulated in intracranial aneurysms relative to the levels in normal Circle of Willis arteries." (PMID 23516489, 2013). "The results showed that SPARC, MMP-2 and MMP-9 were strongly expressed in intracranial aneurysm tissues; however, these proteins were expressed minimally or not at all in normal Circle of Willis arteries." (PMID 23516489, 2013). "By reporting morphological evidence of high level of SPARC, MMP and MMP9 in these patients, our results may yield important sight into pathogenesis of intracranial aneurysms and open avenues for the investigation of new therapeutics in this disease." (PMID 23516489, 2013).
intracranial aneurysms (continued). "Since neovascularization includes endothelial cell invasion and ECM remodeling, it was not surprising to find that SPARC is expressed by endothelial cells in culture and in tissues, But no research reported if SPARC is a contributor of intracranial aneurysm." (PMID 23516489, 2013). "The present study showed that SPARC expression in cerebral aneurysms is significantly correlated with MMP-2 and MMP-9 expression (P<0.05), and MMPs are by far the proteases that are the most closely related to the pathogenesis of intracranial aneurysms." (PMID 23516489, 2013).
lymphoma (5 papers, 2013 to 2025). A malignant (clonal) proliferation of B- lymphocytes or T- lymphocytes which involves the lymph nodes, bone marrow and/or extranodal sites. "The dual nature of SPARC highlights its context-dependent function in lymphoma progression and response to therapy." (PMID 40299416, 2025). "This suggests that both the ECM component FN1 and the ECM remodelling SPARC can influence the survival of lymphoma cells and their interactions with the microenvironment." (PMID 24499539, 2013). "Additionally, osteonectin, known as a secreted protein acidic and rich in cysteine (SPARC), is highly expressed by TAMs within the lymphoma TME." (PMID 40299416, 2025). "With respect to immune cells, reports have demonstrated that in lymphoma, the absence of SPARC promotes aberrant interactions between NETs and CD5+ B cells." (PMID 37958984, 2023).
osteogenesis imperfecta (5 papers, 2021 to 2023). Osteogenesis imperfecta (OI) comprises a heterogeneous group of genetic disorders characterized by increased bone fragility, low bone mass, and susceptibility to bone fractures with variable severity. "SPARC mutations have been identified in patients with osteogenesis imperfecta and idiopathic osteoporosis." (PMID 36722472, 2023). "Recently, using whole-exome sequencing, mutations in the gene encoding SPARC were identified in two individuals with recessive osteogenesis imperfecta (OI) type IV." (PMID 34205668, 2021).
papillary thyroid cancer (5 papers, 2019 to 2021). "Silencing MCM3AP-AS1 expression inhibits cell proliferation and colony formation by regulating the miR-138-5p/FOXK1 axis in pancreatic cancer and plays the same role by controlling the miR-211-5p/SPARC pathway in papillary thyroid cancer." (PMID 34692706, 2021). "Cell proliferation and invasion are enhanced by the activation of the miR-211-5p/SPARC pathway in papillary thyroid cancer." (PMID 34692706, 2021). "MCM3AP-AS1 significantly promotes tumor growth by activating the miR-211-5p/SPARC pathway in papillary thyroid cancer." (PMID 34692706, 2021). "For example, MCM3AP-AS1 promotes the progression of papillary thyroid carcinoma by regulating the miR-211-5p/SPARC axis." (PMID 34660700, 2021). "MCM3AP-AS1 was downregulated in papillary thyroid cancer and could serve as a ceRNA of miR-211-5p to upregulate SPARC, thereby aggregating disease conditions." (PMID 34256796, 2021).
adenoma (4 papers, 2010 to 2020). A neoplasm arising from the epithelium. "Deficiency of SPARC augments enterocyte movement in Apcmin/+ mice, thereby suppressing adenoma formation." (PMID 20442768, 2010). "Immunohistochemistry for SPARC showed similar mild positive reaction in epithelial cells in adenoma, AEM and AEC." (PMID 33322258, 2020). "SPARC has been found up-regulated in colorectal tumors and was identified as one of the genes that specifically discriminated between adenomas and carcinomas." (PMID 31554208, 2019). "Among them, SPARC and SPON2 were down-regulated in adenoma and AEM, and up-regulated in AEC and advanced carcinoma." (PMID 33322258, 2020). "Some of these genes have already been reported in adenoma compared to carcinoma, such as SPON2, SPP1, and SPARC, which is validation for our own analysis." (PMID 30175151, 2018). "Moreover, SPON2 and SPARC showed up-regulation in AEC and advanced carcinoma, and down-regulation in adenoma and AEM." (PMID 33322258, 2020). "The aim of this study was to determine whether the expression of selected ECM-related genes (DCN, EPHA4, FN1, SPARC, SPON2, and SPP1) was similar in adenoma and AEM but differed from the expression in AEC and advanced carcinoma." (PMID 33322258, 2020).